MRFAP1L1 (Morf4 family associated protein 1 like 1)
Synonyms: PP784; MGC9651
Tractability: PROTAC: ubiquitination databases record sites on it.
Gene: Protein-coding gene on chromosome 4 (6,707,693 to 6,709,923, reverse strand). Ensembl gene ENSG00000178988.
Gene Ontology:
Molecular function: identical protein binding; protein binding
Genetic constraint (gnomAD): Loss-of-function variants: 9 observed, 11.45 expected, observed/expected ratio (o/e) 0.79, 90% interval 0.47 to 1.37. The upper end of that interval is the gene's LOEUF score, 1.37, which puts it in group 5 of 6, group 1 being the genes least tolerant of losing a copy. Missense variants: 177 observed, 183.59 expected, observed/expected ratio (o/e) 0.96, 90% interval 0.85 to 1.09. Synonymous variants: 78 observed, 75.78 expected, observed/expected ratio (o/e) 1.03, 90% interval 0.86 to 1.24.
Homologues: Orthologues: chimpanzee MRFAP1L1 (100% identical), macaque MRFAP1L1 (100% identical), mouse Mrfap1 (76% identical). Paralogues in human: MRFAP1 (85% identical), MRFAP1L2 (42% identical).
Diseases named in the same sentence as MRFAP1L1 in open-access papers:
MRFAP1L1 is named in the same sentence as 5 diseases in open-access papers, as found by Europe PMC text mining. Sharing a sentence is not in itself a finding about the gene and the disease. The quoted sentences say what the papers report.
breast carcinoma (1 paper, 2024). "MRFAP1L1 and DYNC2LI1 show promise as potential biomarkers, although no studies have yet indicated an association with breast cancer." (PMID 39720180, 2024).
serous ovarian cancer (1 paper, 2021). "In the serous ovarian cancer patients of cohort 2 (n = 20/80), detectable antibodies (Z-scores > 0) were seen against CTAG2 (n = 3/20, 15%), SHARPIN (n = 2/20, 10%), PNMA2 (n = 2/20, 10%), MAGEB4 (n = 1/20, 5%), MRFAP1L1 (n = 1/20, 5%), SERPINB1 (n = 1/20, 5%) and XAGE3 (n = 1/20, 5%)." (PMID 34681879, 2021).
MRFAP1L1 also shares sentences with these, for which no sentence is quoted: cancer (1 paper); ovarian carcinoma (1); tumor (1).